CCND1 (cyclin D1)
Diseases named in the same sentence as CCND1 in open-access papers (continued):
Sharing a sentence is not in itself a finding about the gene and the disease.
breast cancer (continued). "AMPK is activated and cyclin D1 is downregulated in a metformin-resistant breast cancer cell line." (PMID 19046439, 2008). "Breast cancer cases known to express Cyclin D1 served as positive control for Cyclin D1." (PMID 19032735, 2008). "A potential adverse effect of tamoxifen in CCND1 amplified breast cancers is indeed intriguing." (PMID 18823530, 2008). "Excess accumulation of CCND1 in a cell due to either amplification of CCND1 gene or over-expression of its protein product has been frequently found in various cancers, including breast cancer." (PMID 18194538, 2008). "CCND1.COMT interaction in breast cancer cases from Ontario and Finland populations." (PMID 18194538, 2008). "To further prove that the demethylating treatment did not result in unspecific upregulation of gene expression, we determined the expression of the growth promoting gene cyclin D1, which is a direct read-out gene of active Wnt signaling and whose expression is commonly elevated in breast cancer." (PMID 18990230, 2008). "In this study the first subgroup, so-called luminal subtypes (A and B), makes up the hormone receptor-expressing breast cancer and has expression patterns reminiscent of the luminal epithelial component of the breast (including luminal cytokeratin 8/18 and cyclin D1 genes)." (PMID 18510725, 2008). "Decrease in cyclin D1 and upregulation of cytokeratins, Bad and Bax with VN/14-1 may be responsible for the efficacy of this compound in inhibiting breast cancer cell growth in vitro and in vivo." (PMID 17387344, 2007). "Additionally, knockdown of Brk decreases epidermal growth factor-induced (or heregulin-induced) cyclin D1 expression in breast cancer cells." (PMID 17997837, 2007). "Cyclin D1 is a well-known oncogene, which is commonly over-expressed in human breast cancer." (PMID 17147824, 2006). "However, both the cyclin D1 nulls and the cyclin D1-KE mice are unable to support Her2/Neu induced mammary tumor formation, indicating that CDK4 activity is required for this oncogenic event in mice." (PMID 16863592, 2006). "In human breast cancers, gene expression analyses of several hundred specimens showed that transcriptional modulatory function of cyclin D1 may play an influential role in this tumor type." (PMID 16863592, 2006). "The concept that cyclin D1 regulates PPARγ function has additional implications for breast cancer, wherein PPARγ is known to promote breast epithelial cell differentiation, and histological analyses of breast cancer specimens revealed that PPARγ is reduced in tumors with a high cyclin D1 index." (PMID 16863592, 2006). "Thus, while the relative impact of cyclin D1 mediated transcriptional control versus CDK4 modulation in breast cancer awaits further investigation, an abundance of observations support a role for cyclin D1 in transcriptional control for human tumors." (PMID 16863592, 2006). "The findings presented in this study suggest that HDAC inhibitors may have therapeutic potential as cyclin D1 ablative agents for the treatment of breast cancer." (PMID 16504004, 2006). "Culture of MCF-7 breast cancer cells with 1 μM TSA for 6 h resulted in a reduction of cyclin D1 level within both fractions, while treatment with 50 μM MG132 (a proteasome and cathepsin inhibitor) resulted in increased levels of the cyclin D1 within the nuclear fraction." (PMID 16503970, 2006). "Cyclin D1 has been shown to play an important role in breast cancer cell proliferation." (PMID 16504004, 2006). "Overexpression of cyclin D1 seems to have a causative role in breast cancer formation, since mice containing a mammary-gland targeted MMTV-cyclin D1 transgene develop mammary tumors at higher incidence (5 out of 9 transgenic mice compared to none of 15 non-transgenic controls)." (PMID 16536875, 2006).
breast cancer (continued). "Cancer development and progression is a multi-step process, therefore, since both cyclin D1 and cortactin are overexpressed in most breast carcinomas with 11q13 amplification, their cooperative action might contribute to breast cancer development." (PMID 16536875, 2006). "In a second study, oral contraceptive use was associated with an increased risk of breast cancers with CCND1 overexpression, but was unrelated to those without CCND1 overexpression." (PMID 16495921, 2006). "Signalling through ERK5 contributes to cyclin D1 regulation in breast cancer cells." (PMID 15280923, 2004). "Despite ERα expression some tumours do not respond to tamoxifen and we therefore delineated the potential link between the cell cycle regulator and ERα co-factor, cyclin D1, and tamoxifen response in a material of 167 postmenopausal breast cancers arranged in a tissue array." (PMID 15138475, 2004). "Cyclin D1 knockout mice show a marked defect in breast epithelium development during pregnancy and tissue-specific overexpression of cyclin D1 leads to mammary hyperplasia and adenocarcinoma formation in mice models, supporting the relevance for cyclin D1 in breast cancer development." (PMID 15138475, 2004). "CCND1 may serve as a molecular marker for predicting hormone responsiveness in breast cancer, as hypothesis currently being tested in a large and homogeneous clinical study." (PMID 11870541, 2002). "Since cyclin D1 staining is associated with OR positivity, overexpression of cyclin D1 is likely indicating a beneficial response to tamoxifen when all breast cancers, OR-positive and -negative, are taken together." (PMID 11875707, 2002). "It has, therefore, been hypothesized that tamoxifen treatment of breast cancer may be inefficient in tumour cases that harbour genetic lesions which result in elevated levels of cyclin D1 or A, or that lead to reduced levels of cdk inhibitors p21 or p27." (PMID 11875707, 2002). "The antiproliferative effects of gossypol on human MCF-7 mammary cancer cells and cyclin D1-transfected HT-1060 human fibrosarcoma cells were investigated by cell cycle analysis and effects on the cell cycle regulatory proteins Rb and cyclin D1." (PMID 9218727, 1997). "A high proportion of breast tumours with a low grade of malignancy in this series of operable breast cancer patients may explain discrepancies concerning the prognostic value of amplification and of overexpression of cyclin D1." (PMID 8611372, 1996). "By regulating the G1/S phase, cyclin‐dependent kinase 4 (CDK4) and CDK6 may participate in breast cancer cell metastasis, high Cyclin D1/CDK4 complex levels increase glioblastoma cell metastasis, and RUNX2 promotes PCa cell bone metastases and tissue invasion of C4‐2B and LNCap PCa cells." (PMID 39949984, 2025). "We demonstrate that ErbB2 levels determine the relative contributions of CDK4-cyclin D1 and c-Myc pathways, with distinct temporal dynamics and reversibility patterns that have not been previously characterized in the context of ErbB2 heterogeneity within luminal A breast cancer." (PMID 41161384, 2025). "Beyond its therapeutic potential, circFOXK2 expression could serve as a biomarker to identify patients who are most likely to benefit from circFOXK2-based therapies, particularly those with high circFOXK2 and CCND1 expression and resistance to endocrine treatments in breast cancer." (PMID 40233410, 2025). "Moreover, STAT3 upregulates cyclin D1 to regulate cell cycle progression in breast cancer." (PMID 39768178, 2024).
breast cancer (continued). "To assess whether similar mechanisms of action occurred also in BC upon Bio-nFeR treatment, we performed immunoblot analysis of mammary tumors ex vivo for key factors involved in cellular proliferation and biosynthesis such as pERK, p38, p16, Cyclin D1, mTOR, 4EBP1, and S6RP." (PMID 39497135, 2024). "Additionally, we observed that GSK126 treatment resulted in increased levels of CCND1 in the breast cancer line MDA-MB-231 and the SV40-immortalized monkey kidney fibroblast cell line COS7, suggesting that PRC2 activity can repress CCND1 expression in multiple mammalian cell lineages and species." (PMID 38562687, 2024). "Thus, cyclin D1 overexpression is reported in around 50% of breast carcinoma." (PMID 40034931, 2024). "In addition, LAPATINIB has been shown to reduce the expression of CCND1 in breast cancer." (PMID 37324256, 2023). "In addition, cyclin D1 is an AR target gene, downregulated by androgens in ER+ breast cancer cells." (PMID 37686282, 2023). "Interestingly, we show that the effects of CCNI on the growth of animal models of triple‐negative breast cancer are similar to the ones promoted by CCND1, the deregulation of which is a breast cancer hallmark." (PMID 37081792, 2023). "Additionally, progesterone receptor B signaling could negatively regulate breast cancer cell migration and metastasis by affecting the Cyclin-D1/Cdk4/Paxillin interaction and Paxillin phosphorylation." (PMID 36869991, 2023). "EIF4E may be an important regulator of angiogenic factor (such as IL-8 and VEGF) production in breast cancer cells, affecting angiogenesis by regulating the translation of its target mRNAs (VEGF, Cyclin D1 and FGF2), and is associated with a poor prognosis in breast cancer." (PMID 36052258, 2022). "Moreover, over 50% of breast cancer cells overexpress cyclin D1." (PMID 33407601, 2021). "Apelin stimulates MCF-7 BC cell proliferation via the dose-dependent induction of cyclin D1 and amplified in breast cancer 1 (AIB1) and invasion potential by upregulating MMP1 expression, a mechanism also described in A549 lung adenocarcinoma cells." (PMID 33670492, 2021). "Besides, in human breast cancer cell line MDA-MB231, G1 arrest induced by α-mangostin was associated with the augmentation of p21waf1/cip1, a decreased expression of proliferating cell nuclear antigen (PCNA) and cyclin D1." (PMID 34885809, 2021). "In the present study, we have collected CCND1 SNPs data from the NCBI genome workbench and applied in silico analysis on coding nonsynonymous SNPs, splice site SNPs and 5′ and 3′ UTR SNP to predict their pathogenic impact on protein structure and function in relation with breast cancer." (PMID 33438725, 2021). "The mean rank levels for miRNA-373, VEGF, and cyclin D1 were investigated regarding clinico-pathological factors (age, menopausal status, pathological types, clinical stage, histological grading, and hormonal receptor status) among the primary breast cancer group." (PMID 34089425, 2021). "Moreover, mice lacking CCND1 gene, which encodes the cyclin D1 protein, were unable to develop mammary tumors dependent upon ErbB2 or RAS." (PMID 33805800, 2021). "Therefore, Cyclin D1 could act as an important downstream effector to mediate the suppressive role of ELF5 in breast cancer progression." (PMID 33742100, 2021). "Finally, gene expression data analysis from the breast cancer cell line dataset and copy number variation from the cancer cell line encyclopedia dataset similarly demonstrated increased expression/CN variation of CCND1 and YWHAZ in TNBC cell lines." (PMID 34350123, 2021).
breast cancer (continued). "These putative oncogenic roles generally result from cyclin D1 overexpression, and the mechanisms of overexpression are largely unknown, although genomic CCND1 amplification or translocation accounts for overexpression in subsets of human cancer, including breast cancers and lympoma." (PMID 33947829, 2021). "Similarly, another clinical trial in breast cancer patients treated with a high dose of atorvastatin (80 mg/day) in the first 2 weeks before surgery suggested that this treatment decreased breast cancer proliferation by influencing the expression of cyclin D1 and p27." (PMID 34303383, 2021). "Additionally, PI3K, MEK, p38 and cyclin D1 activation has been described as result of TIMP1 activity in different breast cancer cells, including MDA-MB-231, providing the molecular basis mediating the proliferation inhibition observed in our experimental models." (PMID 32012729, 2020). "Thus, a novel cyclin D1/miR-17-5p/miR-20 forms a regulatory feedback loop in breast cancer." (PMID 32575745, 2020). "Accumulating studies revealed that cyclin D1 was upregulated in various cancers, including breast cancer, melanoma, colorectal cancer, lung cancer, oral squamous cell carcinoma, as well as NPC20, 21, 22; Thus, it might be indicative of the clinical prognosis in NPC." (PMID 32697404, 2020). "Notably, 1/3 of FGFR1-amplified tumors harbor amplification of CCND1 in breast cancer." (PMID 32380883, 2020). "Amplification of CCND1 occurs in ~15% of breast cancer (BC) and overexpression in a larger proportion has been associated with resistance to endocrine therapy." (PMID 32307447, 2020). "Therefore, to investigate whether Cyclin D1 proteolysis induced by SHP2 knockout in breast cancer cells might be associated with T286 phosphorylation, we treated the cells with MG132 and then examined the expression of phosphorylated Cyclin D1." (PMID 32944401, 2020). "Moreover, breast cancer with Myc and/or CCND1 exhibited poorer overall prognosis." (PMID 31462314, 2019). "Interestingly, tRXRα-expressing THP-1 cells could also promote the expression of c-Myc and cyclin D1 and growth and invasion of breast cancer cells, indicating that the effect of tRXRα in macrophages is not limited to colon cancer." (PMID 30931933, 2019). "Here, we have provided novel insights on the crosstalk that may occur between AHR and GPER upon exposure to 3MC, toward the up-regulation of CYP1B1 and cyclin D1 expression as well as the proliferative effects observed in breast cancer cells and main components of the tumor microenvironment as CAFs." (PMID 31370872, 2019). "Therefore, it could be inferred that the downexpression of Mcl-1 and cyclin D1 was also involved in autophagic cell death in dovitinib-treated breast cancer cells." (PMID 31485222, 2019). "Similarly, cyclin D1 overexpression augments breast cancer in transgenic mice." (PMID 30718920, 2019). "In conclusions, the expression of CCND1 and ER activity following neoadjuvant endocrine therapy may be associated with the efficacy of chemo-endocrine therapy in post-menopausal patients with ER-positive and HER2-negative breast cancer." (PMID 31112577, 2019). "However, clear biomarkers of response to palbociclib treatment have yet to be identified, and neither amplification of CCND1 (coding for cyclin D1) or loss of p16 were definitively linked to response in breast cancer trials." (PMID 31727874, 2019). "Compared with normal mammary tissues, cyclin D1 was overexpressed in asynchronous cultured cells from Brca1-mutant tumors, but cyclins A, B1, and E were not detectable, indicating that mammary tumors caused by the loss of BRCA1 are associated with a deficiency of cyclin B116." (PMID 30327455, 2018). "BTG1 expression was down-regulated in breast cancer cells and significantly correlated with proliferation, poor overall survival, histological grade, clinic stage, and lymph node metastasis by regulating protein expression levels of Cyclin-D1, Bcl-2, and MMP-9." (PMID 29416786, 2018).
breast cancer (continued). "Knockdown of Cyclin D1 could abolish the MDR phenotypes of breast cancer cells." (PMID 28334049, 2017). "This indicates that high cyclin D1 expression is linked to an activated cell cycle and worse prognosis of breast cancer in ER-positive disease, while cyclin D1 expression does not associate to markers of cell cycle activation or prognosis in ER-negative tumors." (PMID 28528450, 2017). "Curiously, forced expression of a cyclin D1 mutant, defective in cdk binding, is also sufficient for the induction of mammary tumors with similar latency suggesting additional cdk-independent functions, such as the induction of chromosomal instability may contribute to the pro-oncogenic phenotype." (PMID 29137223, 2017). "To date, several meta-analyses have demonstrated that various biomarkers may be associated with the survival of patients with breast cancer, including p27, vascular endothelial growth factor (VEGF), Cyclooxygenase (COX-2), B cell lymphoma 2 protein (BCL-2), and cyclin D1." (PMID 28410191, 2017). "Furthermore, we observed that cfDNA could promote the proliferation of hormone receptor positive (HR+) breast cancer cells by the activating toll-like receptor 9 (TLR9)-nuclear factor kappa B (NF-κB)-cyclin D1 pathway." (PMID 28574818, 2017). "In addition, cfDNA could stimulate the proliferation of HR+ breast cancer cells by activating the TLR9-NF-κB-cyclin D1 pathway." (PMID 28574818, 2017). "Furthermore, we showed cfDNA could promote HR+ breast cancer cell proliferation by activating the TLR9-NF-κB-cyclin D1 pathway." (PMID 28574818, 2017). "Therefore, the novel allosteric regulation of cyclin D1 translation by DCB-3503 may be used alone or in combination for the treatment of HCC or breast cancer with cyclin D1 amplification." (PMID 27596272, 2016). "However, primary breast cancers are usually positive for ER, PR, C-erbB2, Cyclin D1, and so on." (PMID 27583877, 2016). "With regard to breast cancer, elevated Sp1 was found to regulate thousands of genes that are critically involved in mammary tumorigenesis and metastatic progression, such as vascular endothelial growth factor, urokinase plasminogen activator and its receptor, cyclin D1 and BRCA1." (PMID 25918249, 2015). "Notably, significantly lower levels of cyclin D1 protein were observed in all four breast cancer cell lines treated with phenformin, which suggested that phenformin might regulate the cell cycle of breast cancer cells by modulating cyclin D1." (PMID 26114294, 2015). "In vitro, VDR activation in breast cancer cells reduced β-catenin activation and transcriptional activity leading to elevated expression of the extracellular Wnt inhibitor dickkopf-related protein 1, and a reduction in the interaction of β-catenin with the cyclin D1 promoter." (PMID 26008979, 2015). "Results strongly suggest the ERα-coupled Bmi1 regulatory pathway may be one of the main regulatory mechanisms in breast cancer, whose activity determines the down-stream gene status of p16INK4a and cyclin D1, and consequently impacts the biologic behavior of breast cancer." (PMID 24559156, 2014). "Since cyclin D1 was reported to play a significant regulatory role during progression through the G1 phase of breast cancer cells, we next examined whether the expression of cyclin D1 was responsible for the G0/G1 cell cycle arrest in Smurf2 siRNA-treated cells." (PMID 25191523, 2014). "Upregulation of miR-96 in breast cancer cells modulates their entry into the G1/S transitional phase, which is caused by downregulation of cyclin-dependent kinase (CDK) inhibitors, p27(Kip1) and p21(Cip1), and upregulation of the cell-cycle regulator cyclin D1." (PMID 24678958, 2014). "Moreover, it is unknown whether TSC inhibits breast cancer cell proliferation through the down-regulation of Cyclin D1." (PMID 25101695, 2014).